ATM (ATM serine/threonine kinase)
Diseases named in the same sentence as ATM in open-access papers (continued):
Sharing a sentence is not in itself a finding about the gene and the disease.
cancer (continued). "However, in cancer patients, the functional relevance of most tumour ATM alterations is unknown." (PMID 37627223, 2023). "The goal of this study was to comprehensively analyze the synergistic relationship between the inhibitors of canonical DDR kinases (ATM, ATR, and DNA-PK) and a panel of anti-cancer drugs." (PMID 38097586, 2023). "This may be reflective of selection on the basis of protein ATM expression, instead of selecting on the basis of ATM inactivating mutations, and/or may reflect the schedule of ATR inhibitor employed, with potentially more continuous schedules being more optimal for ATM-deficient cancers." (PMID 37773077, 2023). "The DDR pathways are promising targets for anti-cancer therapy, and various DDR-related genes are currently under clinical development, such as PARP, ATM, ATR, DNA-PK, CHK1, CHK2, and WEE1." (PMID 38041093, 2023). "Indeed, it was shown that MSI cancer cells could no longer efficiently repair DSBs in the context of splice-altering mutations in the ATM gene or in the MRE11 gene from the MNR (MRE11/NBS1/RAD50) DNA mutation repair system." (PMID 36833239, 2023). "Our results revealed that in combination with radiation, ATM inhibitors offer a powerful new strategy for enhancement of DSB-mediated micronucleation and the TBK1-dependent inflammatory signaling in cancer cells." (PMID 36656721, 2023). "First, we coinjected immunocompromised mice with 5PT cancer cells, a cell line that promotes myoCAF differentiation, with either control HFFF2 fibroblasts or HFFF2 with ATM shRNA knockdown." (PMID 36353752, 2022). "While phospho-ATM-NEMO-AKT-mTOR signalosome provides growth advantage and treatment resistance to cancer cells, from an immunological perspective, re-activation of AKT can support anti-tumor functional activity of T cells." (PMID 36428727, 2022). "Seven top upregulated emRNAs and related to ccRCC or/and multiple malignant tumors, including CUL9, ATM, ARID1A, KMT2D, PBRM1, PREX2, and SETD2, were selected as candidate biomarkers for further testing." (PMID 36002886, 2022). "Several other studies have provided evidence that DNA damage and stress signal is transmitted from protein kinase (ATM and ATR) and its downstream CHK1 and CHK2 target phosphorylation at different residues in cancer cells." (PMID 35946055, 2022). "In fact, this synergistic effect was lost in cells expressing RYBP and suggests that RYBP sensitizes cancer cells to PARP inhibitor, at least in part, by reducing ATM activity." (PMID 36233063, 2022). "We identified an additional role for ATM in the contribution to junctional diversity during V(D)J recombination, resulting in a shorter CDR3 length which may contribute to the generation of pathology (pathogen, cancer, and autoimmunity)-associated T cell receptors." (PMID 34825286, 2022). "Our dataset highlighted ATM as a potential indicator for TMB-H or hypermutated CRC, evident in early T stage cancers here, and consistent with the data available from TCGA early T stage CRC." (PMID 35740599, 2022). "Aberrant activation of these DDR kinases (ATM, ATR, DNA-PK, CHK1, CHK2, and PARP) in cancer is strongly correlated with resistance to genotoxic cancer therapies, including in GB." (PMID 35406593, 2022). "A comparison of the dose–response landscapes for ATM or MDM2-E2F1 combination with AKT in NT_8 and NT_9 revealed how different cancer networks exhibit different dose sensitivities even to treatments that are optimal for both networks." (PMID 36071176, 2022). "The benefit of targeting homologous recombination pathway alterations has been limited to a few cancers with specific molecular signatures due to dysfunction of the HR pathway (BRCA1/2, ATM and HRD state)." (PMID 36358724, 2022).
cancer (continued). "PTEN, ATM, and BAP1 were the most frequently affected genes pan-cancer (34%, 7%, and 4% of all H1b cases)." (PMID 35681079, 2022). "A recent study demonstrates that the ATM and ATR kinases phosphorylate KIFC1 to maintain the viability of cancer cells with centrosome amplification, which leads to drug resistance and tumor recurrence." (PMID 35327439, 2022). "ATM, which plays an essential role in DSB repair, can be a potential target of cancer chemotherapy, including DDP." (PMID 35303867, 2022). "HDACIs were found to selectively deactivate key regulators of DNA repair proteins such as ATM, MRE11, and RAD50 in cancer cells." (PMID 35897717, 2022). "Due to its ability to inhibit ATM activity, we find that RYBP sensitizes cancer cells to poly-ADP-ribose polymerase (PARP) inhibitors." (PMID 36233063, 2022). "In HR-proficient cancers, induction of synthetic lethality can be achieved through HRR inhibition by using specific inhibitors of ATM, ATR, Topoisomerase 2 or Bromodomain Containing 4 (BRD4) to create a BRCAness phenotype." (PMID 35328658, 2022). "Previous reports also highlighted a deregulation of ATM in PTEN mutant tumors, suggesting that the ATM-PTEN axis is of therapeutic value for certain cancers." (PMID 35477555, 2022). "Torin2 is a potent inhibitor of mTOR, ATM, and ATR and has been previously shown to inhibit the growth of several different cancers." (PMID 35406510, 2022). "Cells from carcinomas adopt the mesenchymal-stem phenotype in response to DDR, ATM, and NF-κB activation and produce IL-6, which promotes persistent proliferative signaling and the fibroblastic shape." (PMID 35806442, 2022). "Molecular inhibitors of ATM/ATR, for example, AZD1390 and VX-970, have been observed to result in both chemosensitivity and radiosensitivity in a wide range of cancer cells." (PMID 33431817, 2021). "At the genetic level, tumor mutation burden and alterations in DNA damage response and repair genes including ATM, ERCC2, BRAC-2, FANCA, MSH6, and POLE can to some extent predict the response of ICIs in specific cancer types." (PMID 33791296, 2021). "Alterations of ATM and BRCA1 gene expression are found in cancers, some of which are correlated with treatment response and patient outcome." (PMID 34068585, 2021). "Thus, HNC patients with low ATM expression may have a reduced response to anti-cancer therapy." (PMID 34068585, 2021). "We detected three frequently (>5%) altered genes (ATM, ERBB2 and PIK3CA) for which targeted therapies are available in other cancer types." (PMID 34771420, 2021). "The inhibition of DNA repair components, including ATM, ATR, Chk1 and Chk2, markedly sensitizes cancer cells to radiation." (PMID 34587992, 2021). "In adult cells, DNA methylation has been extensively demonstrated to be involved in the onset and progression of cancer, mainly through the silencing of tumor suppressor genes such as BRCA1, ATM, and PALB2." (PMID 33808555, 2021).
cancer (continued). "Emerging studies revealed that cancer cells with ALT were hypersensitive to the inhibition of ATR, another component of DNA damage checkpoint-activating kinases other than ATM in human cells." (PMID 34743173, 2021). "Consistently, we found that both the ATM-Chk2 and ATR-Chk1 DDR signaling pathways were strongly activated in the cinobufagin-treated cancer cells, immediately following the generation of cinobufagin-induced DSBs and replication stress." (PMID 34425836, 2021). "However, in some cancer cells that have already escaped those tumor-suppressing mechanisms, ATM signaling may be beneficial for cancer survival, resistance to chemotherapy and radiation, promoting Epithelial-Mesenchymal Transition, proliferation, invasion, and metastasis." (PMID 34070860, 2021). "In response to chemotherapy, KU‐55933 inhibits ATM‐mediated repair signals in the presence of inositol polyphosphate‐4‐phosphatase type II (INPP4B), which has contradictory roles in cancer progression." (PMID 34977872, 2021). "In anogenital cancers, STAT5 downstream targets were recognized as members of the ATM pathway, consequently linking the JAK/STAT pathway with DNA damage." (PMID 34948185, 2021). "Interestingly, loss of ATR does not predispose such individuals to cancer, like loss of ATM." (PMID 34422791, 2021). "After more than a decade of delay between establishing that DDR proteins were desirable cancer therapy targets, potent and selective compounds eventually became available to target ATR, ATM and DNA-PK." (PMID 34298632, 2021). "The activation of ATM and/or ATR contributes to treatment resistance and pathological neoangiogenesis in cancers." (PMID 34483751, 2021). "Overall, the six genes that had PVs with prevalences greater than one percent for any patient cohort (ATM, BRCA1, BRCA2, CHEK2, CDKN2A and FANCA) comprise a heterogenous group of genes that reflect the complexity of this cancer." (PMID 34255164, 2021). "Our study revealed that ATM and ATR induced KIFC1-S26 phosphorylation-dependent centrosome clustering and survival of centrosome-amplified cancer cells after DNA damage." (PMID 33397932, 2021). "Under DNA damaging treatments, the ATM and ATR kinases phosphorylate KIFC1 at Ser26 to selectively maintain the survival of cancer cells with amplified centrosomes via centrosome clustering, leading to drug resistance and tumor recurrence." (PMID 33397932, 2021). "Paradoxically, ATM and ATR are prime cancer drug targets because DDR inhibition enhances efficacy of therapeutic radiation and many chemotherapeutic agents." (PMID 33742106, 2021). "The high ectopic expression of PRCC made cancer cells insensitive to DNA damage, and enhanced the heterogeneity of HCC cells by inhibiting the JNK/ATM/ATR/ATF2 axis." (PMID 34715922, 2021).
cancer (continued). "The relevant differences between the complete absence of ATM and the presence of the inactive form in in vitro and in vivo models need to be explored in more detail to predict cancer predisposition of A-T patients and to discover new therapies for ATM-associated cancer cells." (PMID 34771661, 2021). "The activation of ATM and/or ATR in cancer cells contributes to treatment resistance and is evaluated as prognostic indexes." (PMID 34483751, 2021). "Possibly, regarding this phenomenon, the same gene has opposite prognostic functions in different cancers; however, gene methylation was inversely correlated with expression in most cases, expect for RAD1, ATR, and ATM." (PMID 34869316, 2021). "Next, we applied RT-qPCR to examine the effect of arecoline, the principal alkaloid of ANE, on the expression of ATM and BRCA1 in cancer cells." (PMID 34068585, 2021). "In this study, we found that Ku was able to simultaneously inhibit ATM phosphorylation and enhance AMPK phosphorylation, with both of these activities serving to inhibit the growth of cancer cells." (PMID 33742560, 2021). "In this analysis, we only considered genes that were affected in at least four TCGA cases within a cancer type and therefore only seven genes (BRCA1/2, ATM, ATR, PALB2, CHEK2, BRIP1) were included." (PMID 34572800, 2021). "We also demonstrated that inhibition of ATM kinase induced apoptosis signaling and potentiated cisplatin-induced cytotoxicity in cancer cells, which implies a potential treatment strategy for the HNC patients with low ATM and BRCA1 expression." (PMID 34068585, 2021). "To gain insights, we identify functionally important conserved residues in ATM, ATR and budding yeast Mec1ATR via cancer genome datamining and a functional genetic analysis, respectively." (PMID 33742106, 2021). "Inhibition of either ATM or ATR enhanced the effect of the combination of FUdR and DUTi on cancer cell lethality by 31.2% ± 6.1 (P = 0.0003) and 31.8% ± 6.1 (P = 0.0004), respectively." (PMID 33824328, 2021). "In lung cancer cells, ATM induces JAK/STAT3 signaling pathway through PD-L1 upregulation to activate EMT, thus resulting in resistance of cancer cells in CP therapy." (PMID 32503307, 2020). "In summary, because of availability of clinical trial-ready small molecule compounds, it is very feasible to combine cytotoxic cancer therapy such as radiotherapy with ICB therapy and ATM inhibition." (PMID 32566127, 2020). "Depletion of FANCD2 protein expression significantly suppresses the cancer cell proliferation and tumor colony formation and metastasis potential, as well as cell cycle progression, by involving cyclin-CDK and ATR/ATM signaling." (PMID 32906798, 2020). "The P103 patient, carrier of two VUS (c.4703A>G, p.(His1568Arg), in ATM and c.7667C>T, p.(Ser2556Leu), in APC), had a low-grade hormone-responsive BC and a family history for BC and other cancers." (PMID 32957588, 2020). "The pathways of central carbon metabolism in cancer and cell cycle related to miR-654-3p and the target genes of PTEN and ATM were different between the QXXY and GYPXXY patients." (PMID 33178319, 2020). "In this regard, MDC1, a mediator protein activated as part of ATM-ChK2 pathway is necessary for proper manifestation of the DDR response and can be a limiting factor affecting prognosis of certain cancers." (PMID 32160908, 2020). "There are several studies showing the potential of combination therapy based on irradiation and various DDR inhibitors (DNA-dependent protein kinase (DNA-PK), ATM/ATR, LIG4, PARP1, CHK1) but mainly in other types of cancer." (PMID 32605254, 2020). "CD6, CCL19, CD40LG, XCR1, MAGEA1, ATM and CCL19 genes were significantly differentially expressed in MET-altered cancers." (PMID 33437521, 2020). "We thus evaluated ECO delivery of siRNA targeting ATM and DNApk-cs, two major targets for the radiosensitization of GBM and other cancers." (PMID 33158243, 2020).
cancer (continued). "Accumulating evidence demonstrated that aberrant activation of DDR proteins (ATM, ATR, DNA-PK, Chk1, Chk2 and PARP) in cancer is strongly correlated with resistance to genotoxic anti-tumor therapeutics of cancer cells." (PMID 32664581, 2020). "The pathways of central carbon metabolism in cancer, cell cycle related to miR-654-3p, and the target genes of PTEN and ATM were different between QXXY patients and GYPXXY patients." (PMID 33178319, 2020). "Here we discuss the experimental evidences supporting this mode of action and their implications in the design and use of specific kinase inhibitors for ATM, ATR and DNA-PKcs for cancer therapy." (PMID 32015826, 2020). "In particular, PIK3CA H1047L, ATM R2443Q, and ERBB3 V104M are well-documented substitutions that are found in both cancer and hereditary disease." (PMID 33009502, 2020). "The kinome profiling with KSEA and PTM-SEA further indicated cancer-specific activation of kinases in DDR signaling, such as ATM and ATR (bold font), which agreed to the results of the initial phosphoproteomic analysis." (PMID 32089736, 2020). "We have also observed that UBR5 interacts with DNAPK, a molecule known to be activated during DNA damage responses, which further supports a role for UBR5 in ATM and DNA-PK mediated H2AX-phosphorylation, as well as cancer development and progression." (PMID 32867711, 2020). "N-Myc overexpression antagonizes the ADIS by downregulating ATM and then facilitates the evasion of senescence and promotes the outgrowth ADT-resistant cancer cells." (PMID 30657058, 2019). "Overexpression of GLI1 plays a crucial role in the ATM-mediated DNA damage response (DDR) signaling, anti-apoptosis, drug resistance, EMT, and cancer stemness, resulting in cancer cell survival and progression." (PMID 31783569, 2019). "Inhibitors of other potential DDR targets including PARP, CHK1/2, WEE1, and DNA-PKcs are considered as novel therapeutic approach for development of ATM and ATR inhibitors with the potential to improve cancer outcome." (PMID 30975222, 2019). "Among these genes, the ATM and MYC co-appear with item ‘cancer’ for 1377 and 1978 times, with ‘breast’ for 408 and 383 times respectively." (PMID 31088372, 2019). "Sensitizing cancer cells to DNA-damaging agents, such as IR, can be achieved by directly targeting key proteins of the DDR, including the ATM and ATR kinases or RAD51 recombinase." (PMID 31993371, 2019). "Two gain regions contained the well-known oncogenes EGFR (7p11.2) and CCND1 (11q13.3) and several known cancer suppressor genes, such as FHIT (3p14.2–p12.1), FAT1 (4q35.1), CDKN2A (9p21.3), and ATM (11q22.3–q24.3), reside within the 10 deletion regions." (PMID 31159251, 2019). "In these cancers, we again observed significant positive correlation of CTL score with ATM protein levels." (PMID 29615613, 2018).